SMAD4 (SMAD family member 4)
Diseases named in the same sentence as SMAD4 in open-access papers (continued):
Sharing a sentence is not in itself a finding about the gene and the disease.
hereditary hemorrhagic telangiectasia (continued). "Hereditary hemorrhagic telangiectasia (HHT, Osler–Weber–Rendu syndrome) is an autosomal-dominant vascular disorder caused by heterozygous loss-of-function mutations in activin receptor-like kinase 1 (ALK1), endoglin (ENG), or SMAD4." (PMID 37219736, 2023). "In addition, most individuals with a pathogenic SMAD4 variant present with a combined syndrome of JPS and hereditary hemorrhagic telangiectasia (JPS/HHT)." (PMID 36359527, 2022). "Although the majority of BAVMs arise sporadically, they also occur in patients with Hereditary Hemorrhagic Telangiectasia (HHT), a Mendelian disorder inherited in an autosomal dominant fashion and caused by mutations in one of three genes (ACVRL1, ENG and SMAD4) in the TGFβ signaling pathway." (PMID 24098321, 2013). "The 24 patients receiving elective surgery were aged 17–80 years (mean 39 years), 11 (46%) were male, and 17 had confirmed hereditary hemorrhagic telangiectasia (HHT) spanning ACVRL1, ENG and SMAD4 genotypes." (PMID 39777301, 2025).
lung carcinoma (70 papers, 2005 to 2025). "In lung cancer, loss of SMAD4 function accelerates metastasis, and it was found that SMAD4 mediates metastatic signalling through the PAK3-JNK-Jun pathway." (PMID 37685308, 2023). "The AHR pathway is a sensor and regulator of the defence system against xenobiotic chemicals and is also linked with TGF-β signalling to downregulate SMAD4 and impair invasive capacity and activate autophagy in lung cancers." (PMID 36826068, 2023). "Our study showed that the incidence of SMAD4 co-mutations in KRAS-mutant lung-cancer patients was 5.5%, higher than in the NSCLC population at 2.5%." (PMID 35887766, 2022). "We have observed an association of reduced Smad4 expression with lung cancer malignancy in clinical metastatic samples, substantiating the role of Smad4 regulation in lung cancer progression." (PMID 34381046, 2021). "The underlying mechanisms by which Smad4 loss-of-function accelerates lung cancer metastasis is unclear." (PMID 34381046, 2021). "SMAD4 is mutated in human lung cancer, but the underlying mechanism by which Smad4 loss-of-function (LOF) accelerates lung cancer metastasis is yet to be elucidated." (PMID 34381046, 2021). "At 12 months of age, 100% of mice deficient in airway epithelial Smad4 and Pten develop lung cancer with nearly 2/3 show distant metastasis to the stomach, liver, and spleen." (PMID 28824608, 2017). "If asbestos were associated with induction of SMAD4 inactivation in lung cancer, one would expect the inverse association with BMP silencing that we have observed." (PMID 16175182, 2005). "In addition, SMAD4 and its transcription factor play a regulatory function for many target genes, also increasing the risk of cell tumorigenesis in lung cancer." (PMID 35723337, 2022). "Consistent with our data, previous research has shown that SMAD4 reduction is associated with phenotypes such as tumor progression and metastasis in some cancers including lung cancer, therefore is supportive with our findings of PDH inhibition leading to a more aggressive phenotype." (PMID 35083212, 2021). "SMAD4 mutations are uncommon in lung cancer, according to COSMIC database." (PMID 28619094, 2017). "Mutations in Smad2 and Smad4 genes have been found in less than 10% of lung cancers." (PMID 26356817, 2015). "Mutations in Smad2 and Smad4 genes have been found in 5–10% of lung cancers." (PMID 26356817, 2015). "Moreover, it is necessary to determine whether the radiosensitivity is also affected by the mutations of SMAD3 or SMAD4 in other cancers, such as nasopharyngeal carcinoma and lung cancer." (PMID 34434896, 2021). "Functional SMAD4 is a tumor suppressor and its inactivation promotes lung cancer metastasis through de‐repression of PAK3 by miRNA regulation." (PMID 36161776, 2023). "Our data suggest that the PAK3, a downstream effector of SMAD4, mediates lung cancer cell metastasis." (PMID 34381046, 2021). "We conclude that downregulation of Smad4 derepresses the PAK3-JNK-Jun pathway via attenuated production of miR-495/miR-543 in lung cancers." (PMID 34381046, 2021). "TGF-β enhanced the proliferation in lung cancer cell with miR-27a, but the effect was reversed by Smad2 or Smad4 overexpression." (PMID 34712379, 2021).
lung carcinoma (continued). "Taken together, we conclude that Smad4-mediated PAK3-JNK-Jun activation via regulation of miRNA in lung cancers appears to be a mechanism in the development of metastatic human lung cancers." (PMID 34381046, 2021). "This priming effect of the TGFβ‐SMAD4 axis toward YAP/TAZ‐dependent AXL expression was also validated via a meta‐analysis of lung cancer patient clinical data." (PMID 33207077, 2021). "Reexpression of Smad4 significantly attenuated SPK cell migration and invasion in a transwell study, while knocking down Smad4 enhanced invasion in human lung cancer cells." (PMID 34381046, 2021). "Particularly, the activation of TGFβ signaling through SMAD4 after doxorubicin treatment contributed to YAP‐dependent AXL expression in mesenchymal‐type lung cancer cells." (PMID 33207077, 2021). "Particularly, doxorubicin treatment in mesenchymal‐type lung cancer cells also activated TGFβ‐SMAD4 signaling, which in turn primed YAP/TAZ activity toward AXL expression." (PMID 33207077, 2021). "The deletion of Smad4 can promote the formation of lung cancer by inhibiting DNA repair and at the same time make the tumor itself more sensitive to topoisomerase inhibitors, which is related to the regulatory mechanism of DNA repair of Smad4." (PMID 33794845, 2021). "This study provides insights into Smad4-dependent regulation of tumorigenesis, progression, and metastasis in lung cancer." (PMID 34381046, 2021). "Immunohistochemistry was used to detect the expression of Smad4 in lung cancer tissues and normal cancer-adjacent lung tissues." (PMID 33794845, 2021). "A study has confirmed that Smad4 can regulate the metastasis process of lung cancer by inhibiting the expression of VEGF." (PMID 33794845, 2021). "So far, some studies have continuously suggested that there is a complex relationship between lung cancer and DPC4/Smad4, but the research data on the expression of Smad4 in NSCLC and its clinical significance is still insufficient." (PMID 33794845, 2021). "Although O-GlcNAc was shown to disturb the degradation of SMAD4 proteins in A549 lung cancer cells, it was still unclear how O-GlcNAc interrupted SMAD4 degradation." (PMID 33199824, 2020). "In conclusion, the amount of SMAD4 proteins varied according to overall O-GlcNAc status in human A549 lung cancer cells." (PMID 33199824, 2020). "This study showed that the amount of SMAD4 proteins changes according to cellular O-GlcNAc levels in human lung cancer cells." (PMID 33199824, 2020). "SMAD4 protein levels were checked by treating A549 lung cancer cells with inhibitors of O-GlcNAc editing enzymes which caused thiamet-G, an OGA inhibitor, to increase SMAD4 levels whereas SMAD4 levels decreased when treated with OSMI-1, an OGT inhibitor." (PMID 33199824, 2020). "TGF-β2 signals through TGFBR1, TGFBR2, SMAD2, and SMAD4 to upregulate WNT7B mRNA expression in lung cancer cells." (PMID 30971692, 2019). "We found miR-301a was upregulated in both lung adenocarcinoma and squamous cell carcinoma, whereas Smad4 show the downregulation in these two types of lung cancer." (PMID 30185897, 2018). "Of note, the level of miR-301a expression correlated inversely with SMAD4 expression in clinical specimens of human lung cancer." (PMID 30185897, 2018). "miR-301a displayed significantly higher expression in both lung adenocarcinoma and lung squamous cell carcinoma compared to normal tissue, whereas its target genes, SMAD4 was significantly downregulated in lung cancer sample compared to normal tissue." (PMID 30185897, 2018). "Our recent study demonstrated that miR-224 promotes lung cancer cell's migratory, invasive and proliferative capacity and in general tumor growth both in vitro and in vivo by direct targeting of SMAD4 and TNFAIP1." (PMID 26307684, 2015).
lung carcinoma (continued). "For example, SMAD4, the effector protein in the BMP pathway, has been identified as mutated and deleted in lung cancer." (PMID 16175182, 2005). "Myc inhibitor acts as a potential therapeutic drug for SMAD4-mediated resistant lung cancer." (PMID 38233864, 2024). "Analysis indicated that CDKN2A, FAT1, MSH6, ARID1A, KEAP1, NF1, and SMAD4 mutation was more recurrent in patients with ERBB2 SNV/indels within the kinase domain compared with non-kinase domain in lung cancer." (PMID 35911441, 2022). "The action of Smad4 in the regulation of PAK3 offers a tool for lung cancer prognosis." (PMID 34381046, 2021). "miR-301a and SMAD4 could be a therapeutic target for preventing and curing the lung cancer developing with chronic exposure of arsenic." (PMID 30185897, 2018). "Given pulmonary tissue is considered to be the most sensitive site for arsenic toxicity, and long-term arsenic exposure significantly increases the risk of lung cancer, we compared the expression level of miR-301a and Smad4 in patients with lung cancer from TCGA." (PMID 30185897, 2018). "All these data indicated that re-expression of miR-205 could promote lung cancer cell growth in vivo by inhibiting the expression SMAD4." (PMID 28199217, 2017). "The positive expression rate of TβRII and Smad4 in the poorly-differentiated lung carcinoma group was significantly lower when compared with the well- and moderately-differentiated lung carcinoma groups, exhibiting a statistically significant difference (P<0.05)." (PMID 25452807, 2015). "However, there has been no studies showing the contribution of mutation of SMAD4 to the brain metastasis of lung cancer prior to our research." (PMID 36161776, 2023). "USP9X participates in TGF-β signaling by deubiquitylating Smad4 and TGFβR2, or by inducing TGF-β2 transcription, as shown in granulosa cells apoptosis and lung cancer radioresistance." (PMID 40246814, 2025). "LncRNA Smyca functions as a scaffold and facilitates the binding of Smad3 and Smad4, which promotes TGF-β/Smad signaling-mediated EMT and lung cancer cell migration." (PMID 38818471, 2024). "In addition, kaempferol (10, 25, 50 μM) treatment of A549 lung cancer cells, followed by TGFß‐1 stimulation, resulted in phosphorylation of Smad3 (although phosphorylation at residue Thr179 was down‐regulated) and the formation and nuclear translocation of Smad4 complexes." (PMID 37697969, 2023). "Several previous studies have confirmed the cancer-promoting role of miR-205-5p in lung cancer, targeting genes such as PTEN, PHLPP2, and SMAD4." (PMID 37670265, 2023). "Efficient ablation of Smad4 in SPK tumors was verified by immunohistochemical analysis of lung cancer tissues from SPK vs. PK mice and by RT-PCR analysis of tumors for Smad4 RNA expression." (PMID 34381046, 2021). "One paper reported that miR-27a upregulated in lung cancer cell lines and patients and impaired TGF-β signaling by inhibiting Smad2 and Smad4, and its overexpression decreased Smad2 and Smad4 mRNA and protein levels." (PMID 34712379, 2021). "Given the inverse correlation between SMAD4 and PAK3 in PK/SPK lung cancer cells, we wondered how PAK3 signaling affects cell migration and invasion." (PMID 34381046, 2021). "In summary, this study identifies an effector of Smad4, PAK3, and a de novo miRNA-mediated mechanism in the regulation of lung cancer metastasis." (PMID 34381046, 2021).
lung carcinoma (continued). "We have validated the role of Smad4 LOF in promoting the invasive and metastatic progression of lung cancer in vitro and in vivo." (PMID 34381046, 2021). "Our results demonstrate that the upregulation of PAK3 by Smad4 LOF in SPK mice was achieved by attenuating SMAD4-dependent transcription of miRNAs that negatively regulate PAK3 expression, ultimately enhancing lung cancer metastasis." (PMID 34381046, 2021). "To evaluate the importance of FSTL1-BMP4-Smad pathway in lung cancer, we first analyzed the prognostic value of FSTL1, BMP4, Smad4, and p-Smad1/5/8." (PMID 28852126, 2017). "MiR-224 has been reported to be up-regulated in several solid tumors including hepatocellular carcinoma, colorectal cancer, breast cancer, and lung cancer, and repressing various targets such as API5, SMAD4, PHLPP1, PHLPP2, RKIP and TNFAIP1." (PMID 26307684, 2015). "However, other research has shown that miR‐224‐5p is decreased in lung cancer cells and TRG‐AS1 promotes lung cancer cell growth by upregulating the oncogene Smad4 through the sequestration of miR‐224‐5p." (PMID 39840666, 2025). "The frequency of positivity for MUC6 and preserved SMAD4 was low and, in comparison, not that different between primary lung cancers and pulmonary metastases from the GI tract." (PMID 37349623, 2024). "In addition to SMAD3, SMAD4 and SMAD7 are also involved in a range of biological behaviours in lung cancer." (PMID 37685308, 2023). "A study comparing gene expression in lung tissues by microarray analysis from five patients with both lung cancer and IPF revealed five genes e.g. SMAD4, P21, MT1A, MMP7 and TIMP1; these were down-regulated in cancer tissue in comparison to IPF, in at least two of the patients." (PMID 33905434, 2021). "Therefore, our data suggest that PAK3 acts in signal transduction between Smad4 and the JNK-Jun signal pathway in lung cancer cells." (PMID 34381046, 2021). "The expression level of Smad4 in the serum and lung cancer tissues of patients with lung cancer was lower than that in the non-tumor group." (PMID 33794845, 2021). "TOB1 could inhibit the proliferation and metastasis of lung cancer cells through a series of downstream regulators, including cyclin D1, AKT signal transduction, BCL-2, BCL-XL, and SMAD4." (PMID 34604392, 2021). "An inverse correlation between Smad4 and PAK3 pathway components is observed in human lung cancer." (PMID 34381046, 2021). "Even basal levels of YAP reporter activity were significantly modulated by SMAD4 knockdown in TD cells, suggesting that constant SMAD4‐dependent gene transcription contributed to maintaining high YAP activity in mesenchymal‐type lung cancer cells." (PMID 33207077, 2021). "Mice with a homozygous deletion of Smad4 alone in lungs after adeno-Cre treatment survived beyond 52 weeks and didn’t develop any gross anatomic abnormalities or lung cancer (data are not shown)." (PMID 34381046, 2021). "We then checked the interaction between endogenous SMAD4 and GSK-3β in A549 lung cancer cells." (PMID 33199824, 2020). "In addition, SMAD4 also plays an important role in PDAC and lung cancer." (PMID 37962020, 2023). "However, the potential mechanism of Smad4 in lung cancer metastasis has not been elucidated in vivo." (PMID 34381046, 2021). "Therefore repressing Smad2, Smad3, and Smad4 nuclear translocation may regulate EMT-related TGF-β and suppress metastasis and tumor growth in lung cancer." (PMID 32405368, 2020).